CFTR (CF transmembrane conductance regulator)
Diseases named in the same sentence as CFTR in open-access papers (continued):
Sharing a sentence is not in itself a finding about the gene and the disease.
cystic fibrosis (continued). "Previous analysis of CFTR-knockout (CFTR−/−) in piglets has provided important insights into the pathology of cystic fibrosis." (PMID 32712714, 2020). "Since, CaCC-mediated Cl− secretion appears to be preserved in cystic fibrosis its pharmacological stimulation has been suggested as a therapeutic tool for bypassing dysfunctional CFTR." (PMID 32676036, 2020). "Mutations in the cystic fibrosis transmembrane conductance regulator (CFTR) gene decrease the structural stability and function of the CFTR protein, resulting in cystic fibrosis." (PMID 32331485, 2020). "The expression of an apical chloride channel, the cystic fibrosis transmembrane conductance regulator (CFTR), in differentiated cell populations allows for 16HBE to serve as a model for studying cystic fibrosis." (PMID 32985670, 2020). "Cystic fibrosis (CF, OMIM#219700) is an autosomal recessive condition resulting from the pathogenic variants in the CF transmembrane regulator (CFTR) gene." (PMID 32429104, 2020). "Cystic fibrosis is a life-limiting, inherited autosomal recessive disorder resulting from the presence of one or more disease-causing mutations in the cystic fibrosis transmembrane conductance regulator (CFTR) gene." (PMID 32781694, 2020). "Cystic fibrosis, caused by mutations to CFTR, leads to severe and progressive lung disease." (PMID 33239626, 2020). "The effects in the secretion of chloride and bicarbonate anions mediated by the cystic fibrosis transmembrane conductance regulator (CFTR) are present in cystic fibrosis." (PMID 32516941, 2020). "Cystic fibrosis, a genetic disease caused by mutations in the gene coding for the epithelial chloride channel CFTR (Cystic Fibrosis Transmembrane conductance Regulator) is characterized by a disruption of the functions of the respiratory system, digestive tract and reproductive tract." (PMID 32469934, 2020). "Cystic fibrosis (CF; OMIM #219700) is an autosomal recessive hereditary disease in which the molecular genetic basis is a mutation of the CFTR gene (OMIM *602421)." (PMID 32992607, 2020). "Thus, Wisconsin recently launched a project entitled “Assessing the Added Value of Whole Genome Sequencing in Cystic Fibrosis Newborn Screening” to address the hypothesis that identifying non-CFTR genetic variants in individual patients could enlighten therapeutic decision-making." (PMID 32276344, 2020). "Nonsense mutations that lead to the insertion of a premature termination codon (PTC) in the cystic fibrosis transmembrane conductance regulator (CFTR) transcript affect 11% of patients with cystic fibrosis worldwide and are associated with severe disease phenotype." (PMID 33391025, 2020). "Cystic fibrosis is an autosomal recessive disorder affecting the CF transmembrane conductance regulator (CFTR) gene, resulting in alteration of CFTR protein synthesis, processing, or function." (PMID 33374882, 2020). "Although CFTR therapeutics are currently only approved for treating cystic fibrosis, there are efforts to repurpose them for conditions with “acquired” CFTR dysfunction, for example, chronic obstructive pulmonary disease." (PMID 33250777, 2020). "For example, Dekker and colleagues utilized intestinal enteroids derived from patients with cystic fibrosis to assess the responsiveness to CFTR-modulating drugs." (PMID 32244707, 2020). "This fact is explained by the common genetic background, both for cystic fibrosis and CBAVD, namely mutation in the CFTR gene on chromosome 7." (PMID 32722328, 2020). "CFTR encodes an ABC transporter-class Cl− channel and most cases of cystic fibrosis cases are linked to the deletion mutation (F508del-CFTR), which increases CFTR channel protein misfolding and decreases its trafficking out of the ER." (PMID 32759882, 2020). "Since the accelerated cystic fibrosis transmembrane conductance regulator (CFTR) degradation causes the loss of function of CFTR in cystic fibrosis, attenuating the CFTR degradation could be useful for the treatment of CF." (PMID 32331485, 2020).
cystic fibrosis (continued). "Cystic fibrosis could be excluded by sweat tests, additionally, the PCD mutation panel (Blueprint genetics, Espoo, Finland) also covered frequent CFTR mutations (85% of all CF cases), making the existence of CF as a comorbidity very unlikely." (PMID 33243178, 2020). "Perturbation of endothelial function in people with cystic fibrosis has been reported, which may be associated with endothelial cell expression of the cystic fibrosis transmembrane conductance regulator (CFTR)." (PMID 32848840, 2020). "Owing to the development of CFTR modulators in 2009, cystic fibrosis turned from a disease with a high infant mortality rate into a disease with a predicted median survival of 43.6 years." (PMID 33175893, 2020). "CF is a well-characterized, lethal, autosomal, recessive, inherited disorder found predominantly in Caucasians due to mutation in the cystic fibrosis transmembrane conductance regulator (CFTR) gene, characterized by chronic lung bacterial infections." (PMID 32695100, 2020). "Newborn screening for Cystic Fibrosis has been implemented in most programs worldwide, but the approach used varies, including combinations of immunoreactive trypsinogen (IRT) and CFTR mutation analysis on one or more specimens." (PMID 33073036, 2020). "Cystic fibrosis (CF; OMIM: #219700) is a lethal inherited disease caused by pathogenic variants in the CF transmembrane conductance regulator (CFTR) gene, resulting in impairment of CFTR protein expression, function and/or stability." (PMID 33424627, 2020). "CF is an autosomal recessive, multisystem disorder affecting approximately 70,000 individuals worldwide and is caused by variants in the cystic fibrosis transmembrane conductance regulator (CFTR) gene, which encodes an epithelial chloride channel." (PMID 33085659, 2020). "Up to now, the search for drugs to be used for cystic fibrosis therapy was focused on the design and development of small molecules, namely CFTR modulators." (PMID 33291847, 2020). "The first example of nonsense suppression therapy was provided by using the aminoglycoside G418 (geneticin), in cultured cells harboring nonsense mutations in the cystic fibrosis transmembrane conductance regulator (CFTR), whose dysfunction in humans causes the relevant genetic inherited disease." (PMID 31972957, 2020). "Abnormalities in the expression of CFTR also contribute to reduced functionality of the respiratory system, sweat glands, and reproductive system (a classical set of anomalies in cystic fibrosis patients)." (PMID 32722328, 2020). "Mutations in the cystic fibrosis transmembrane conductance regulator (CFTR), a chloride and bicarbonate membrane channel, can cause problems in several organs and lead to cystic fibrosis." (PMID 32811866, 2020). "Thirty years after the identification and cloning of the cystic fibrosis transmembrane conductance regulator (CFTR), a transformational drug therapy for most people with cystic fibrosis received regulatory approval." (PMID 31902693, 2020). "Thus, drugs that can decrease the degradation of ΔF508 CFTR protein, increase the export of ΔF508 CFTR protein to the plasma membrane, and improve its ion channel function, would contribute to restoring the epithelial cell function and alleviating the associated symptoms of cystic fibrosis." (PMID 32780246, 2020). "In addition, it is unclear how loss of function of NDPK will manifest when they bound to partner proteins such as CFTR, whose mutation causes cystic fibrosis." (PMID 31993913, 2020). "Cystic fibrosis is one of the most common life-limiting recessive genetic disorders in Caucasians, caused by mutations in the cystic fibrosis transmembrane conductance regulator (CFTR)." (PMID 32367193, 2020). "The introduction of CFTR modulators in clinical practice has produced a significant impact on short-term clinical outcomes in people with cystic fibrosis." (PMID 32824306, 2020).
cystic fibrosis (continued). "The incidence of cystic fibrosis and the frequency of the variants reported for CFTR depend on the population; furthermore, CF symptomatology is characterized by obstructive lung disease and pancreatic insufficiency among other symptoms, which are reliant on the individual's genotype." (PMID 32596391, 2020). "Among mutations in chromosome 7, impairments in the cystic fibrosis transmembrane conductance regulator CFTR gene are destructive for fertility in cystic fibrosis, when spermatic ducts undergo complete obstruction." (PMID 32722328, 2020). "Cystic fibrosis is a multi-organ disease, with pathological changes occurring in organs that express CFTR, including secretory cells, sinuses, lungs, pancreas, liver and reproductive tract." (PMID 32751630, 2020). "Cystic fibrosis is a genetic disease caused by mutations in the CFTR gene." (PMID 32098269, 2020). "Bronchial hyperreactivity is a common feature of cystic fibrosis and targeting bronchiolar smooth muscle cells with CFTR activators is capable of inducing relaxation symptoms." (PMID 33250777, 2020). "This system was initially established in intestinal organoids to evaluate CFTR functions in patients with cystic fibrosis." (PMID 32801121, 2020). "PSC-derived organoids have been used to model pancreatic facets of cystic fibrosis and to screen a set of cystic fibrosis transmembrane conductance regulator (CFTR) activators." (PMID 32221645, 2020). "Currently, three clinical trials are testing the efficiency of mRNA-based therapies targeting different proteins, including the cystic fibrosis transmembrane conductance regulator (CFTR) via lipid nanoparticle inhalation for the treatment of cystic fibrosis." (PMID 32962254, 2020). "Data from cystic fibrosis patients help reinforce this conclusion, as taking CFTR therapeutics has positive effects on the functional characteristics of their immune cells." (PMID 33250777, 2020). "As a potential target colocalizing with CFTR in cystic fibrosis patients, SLC26A9 is of great value in drug development." (PMID 32818062, 2020). "The pathophysiology of CF is based on defined mutations in the cystic fibrosis transmembrane conductance regulator (CFTR) gene, which cause dysfunction of the CFTR chloride channel and, subsequently, an impaired epithelial chloride and bicarbonate transport resulting in viscid mucus production." (PMID 32457736, 2020). "Defective CFTR protein, responsible for Cystic Fibrosis, is highly expressed in pancreatic ductal epithelial cells (PDECs) but their impact on insulin secreting pancreatic islets is not fully understood." (PMID 31311920, 2019). "Cystic fibrosis is a complex, potentially life-threatening disease which is manifested through mutations in the cystic fibrosis transmembrane conductance regulator (CFTR)." (PMID 31382357, 2019). "CF is caused by mutations in the cystic fibrosis transmembrane regulator (CFTR) gene." (PMID 31687377, 2019). "Cystic Fibrosis is an autosomal recessive genetic disease which results from mutations in the gene encoding the Cystic Fibrosis transmembrane conductance regulator (CFTR, gene ABCC7)." (PMID 31408507, 2019). "Only one in vitro immune cell model of co-infection with different strains of alive P. aeruginosa and A. fumigatus in CF bronchial epithelial cell lines (CFBE cells derived from a cystic fibrosis patient homozygous for the ΔF508 CFTR mutation) has been reported." (PMID 31212791, 2019). "CF is a genetic disease caused by a mutation in the cystic fibrosis transmembrane conductance regulator (CFTR) gene that results in defects of the encoded CFTR protein." (PMID 31551401, 2019). "Genetic defects in cystic fibrosis transmembrane conductance regulator (CFTR) gene cause CF." (PMID 30813645, 2019).
cystic fibrosis (continued). "CF is characterized by mutations in cystic fibrosis transmembrane conductance regulator (CFTR), a chloride channel whose malfunction triggers the activation of transglutaminase-2 (TGM2), as well as the inactivation of the Beclin-1 (BECN1) complex resulting in disabled autophagy." (PMID 31321000, 2019). "Cystic fibrosis is a monogenic autosomal recessive disorder caused by mutations in the CFTR gene." (PMID 31117296, 2019). "The bicarbonate is normally provided by the CFTR channel localized to goblet cell adjacent cells in organs affected by cystic fibrosis." (PMID 30963635, 2019). "It was detected at the apical and basolateral membrane domain in primary differentiated HBE cells derived from cystic fibrosis lungs and in immortalized CFBE41o- cells, a human CF bronchial epithelial cell line derived from a CF patient homozygous for the F508del-CFTR mutation." (PMID 30761001, 2019). "We use multi-DDM to assess the efficacy of different CFTR-modulating drugs in human airway epithelial cells derived from subjects with cystic fibrosis (ΔF508/ΔF508 and ∆F508/-) based on ciliary beat frequency and coordination." (PMID 30992452, 2019). "Defective CFTR triggers aggresome formation and lung inflammation in cystic fibrosis by ROS-TG2-BECN1-mediated inhibition of autophagy." (PMID 31404274, 2019). "Cystic fibrosis is a genetic autosomal recessive disease that induces mutations on a conductance transmembrane regulator protein—cystic fibrosis conductance transmembrane regulator (CFTR)—which controls the excretion of chloride in sweat." (PMID 31057930, 2019). "Calcium-activated anion secretion has been postulated as an alternative to CFTR, with important therapeutic implications in cystic fibrosis." (PMID 31263421, 2019). "Cystic fibrosis is an autosomal recessive, multisystem, genetic disease caused by mutations in the cystic fibrosis transmembrane conductance regulator (CFTR) gene resulting in deficient and/or defective CFTR protein." (PMID 30800069, 2019). "We also tested a set of CFTR correctors from the Cystic Fibrosis Foundation CFTR Chemical Compound Program (cff.org) library, namely C4, C18 and the combination of C4/C1822–24." (PMID 30992452, 2019). "Cystic fibrosis, also commonly referred to as mucoviscidosis, is a multigene related disorder, involving a defect in the CF transmembrane conductance regulator protein, with over 1,500 genes, being identified with the condition." (PMID 31728230, 2019). "The aberrant accumulation of ubiquitinated protein aggregates in cells is a common cause of many degenerative diseases, such as α-synuclein in Parkinson’s disease (PD) and CFTR-ΔF508 in cystic fibrosis 1–3." (PMID 31501480, 2019). "CF is caused by mutations in the cystic fibrosis transmembrane conductance regulator (CFTR) gene protein, typically found in the apical membrane of most epithelial tissues including lungs, submucosal, salivary, gall bladder glands, gut, kidney, pancreas, cervix and uterus." (PMID 31336857, 2019). "Cystic fibrosis is an autosomal recessive disorder caused by mutations in a large gene located in chromosome number 7 encoding a protein called cystic fibrosis transmembrane conductance regulator (CFTR)." (PMID 31126253, 2019). "Complete loss of CFTR protein function leads to the autosomal recessive disease cystic fibrosis." (PMID 31024732, 2019). "One such example is represented by cystic fibrosis (CF, OMIM#219700), an autosomal recessive disorder caused by mutations in the gene encoding for the Cystic Fibrosis transmembrane conductance regulator (CFTR, on chr." (PMID 31134053, 2019). "Small-molecule modulators of cystic fibrosis transmembrane conductance regulator (CFTR) biology show promise in the treatment of cystic fibrosis." (PMID 31413336, 2019). "The selection of these model systems was based on discussions resulting from an international Cystic Fibrosis Foundation workshop centered on CFTR theratyping with applications to both common and rare CFTR variants." (PMID 31307398, 2019).
cystic fibrosis (continued). "Cystic fibrosis transmembrane conductance regulator (CFTR) encodes a chloride channel, expressed in various epithelia, which is defective in patients with cystic fibrosis." (PMID 31214514, 2019). "Lumacaftor, a recently FDA-approved chemical chaperone indicated for cystic fibrosis, was tested against the cystic fibrosis transmembrane conductance regulator CFTR, which is localized to the endoplasmic reticulum and plasma membrane." (PMID 29930256, 2018). "One of the first channels that are identified as intracellular ATP regulated channel is the CFTR channel involved in pathogenesis of cystic fibrosis." (PMID 29641486, 2018). "Notably, we found that ADGRG2 and Gq regulate fluid reabsorption in the efferent ductules via the activation of CFTR, an important ion channel whose mutation leads to cystic fibrosis." (PMID 29393851, 2018). "The genetic disease cystic fibrosis is caused by mutations that affect CFTR anion channels." (PMID 30389955, 2018). "The evaluation of the cystic fibrosis transmembrane conductance regulator (CFTR) function through the sweat test was a milestone for the diagnosis of cystic fibrosis (OMIM: #219700)." (PMID 30217179, 2018). "Our meagre understanding of CFTR misfolding and its reversal by small-molecule correctors hampers the development of mechanism-based therapies of cystic fibrosis." (PMID 30302398, 2018). "Men with CBAVD carrying CFTR mutations have very high chances of successful testicular sperm extraction (TESE), but also significantly increased risks for cystic fibrosis in their children, depending on the CFTR carrier status of their partner." (PMID 29527098, 2018). "Cystic fibrosis has been targeted by AAV-based expression of the cystic fibrosis transmembrane conductance regulator (CFTR) in a number of animal models showing a good safety profile, although no clear clinical benefits." (PMID 29883422, 2018). "Cystic fibrosis is due to the mutation of the gene coding for the CFTR Chloride channel." (PMID 30241412, 2018). "The ATP-gated and cyclic AMP (cAMP)-dependent Cl− channel cystic fibrosis transmembrane conductance regulator (CFTR) participates in Cl− secretion and is broadly known for its role in cystic fibrosis, the pathophysiology of which is due to channel malfunction." (PMID 30404151, 2018). "In contrast to ANO1, the cystic fibrosis transmembrane conductance regulator (CFTR), mutations of which are responsible for cystic fibrosis, is another chloride channel that acts as a candidate tumor suppressor in breast cancer." (PMID 29463274, 2018). "Finally, we assess the ability of XP and E6446 to transfect mRNA encoding the cystic fibrosis transmembrane regulator (CFTR), the protein mutated in CF, into epithelial cells in vitro." (PMID 30059522, 2018). "Cystic fibrosis is an autosomal recessive disorder that may be present in individuals with mutations in the cystic fibrosis transmembrane conductance regulator (CFTR) gene." (PMID 29326970, 2018). "Recently, the role of 14-3-3 in other pathologies has emerged; for example, cystic fibrosis, through the regulation of the trafficking of the cystic fibrosis transmembrane conductance regulator (CFTR) protein." (PMID 29890630, 2018). "Table showing deregulated miRNAs targeting directly or indirectly CFTR in the context of cystic fibrosis." (PMID 30349480, 2018). "The differences in quality control for Cx26 and Cx43 were directly observed for native connexins in human airway epithelial cells derived from a cystic fibrosis patient expressing the CF transmembrane conductance regulator (CFTR) protein harboring the Fdel508 mutation." (PMID 29701678, 2018). "Several mutations in the CFTR (cystic fibrosis transmembrane conductance regulator; ABCC7) chloride channel cause cystic fibrosis, a monogenic disease with high morbidity and mortality." (PMID 30425800, 2018).